RETN (resistin)
Diseases named in the same sentence as RETN in open-access papers (continued):
Sharing a sentence is not in itself a finding about the gene and the disease.
Insulin resistance (continued). "Therefore, resistin might represent a link between inflammation, acute phase response and insulin resistance in critically ill patients." (PMID 19545363, 2009). "Additional modelling for TNFα, resistin, catecholamine infusion rate, age, gender, BMI, operation time, heart/lung bypass time or medication did not further improve the model, suggesting minor contribution of these parameters to the development of insulin resistance in our model." (PMID 19087258, 2008). "Thus, resistin overexpression and hypersecretion induced insulin resistance in adipocytes." (PMID 16854242, 2006). "Hence resistin is a potential mediator of insulin resistance in humans with acute inflammation." (PMID 15578112, 2004). "High VAT content promotes inflammation and tumor progression via cytokine secretion (leptin, resistin, IL-6, and TNF- α), angiogenesis, and insulin resistance." (PMID 40699302, 2026). "Overeating causes the accumulation of liver fats that contribute to the production of most adipokines, such as leptin, resistin, adiponectin, tumor necrosis factor-alpha (TNF-alpha), and IL-6, which are involved in inducing insulin resistance and inflammation." (PMID 41441034, 2025). "Overall, current evidence suggests that resistin plays a role in the pathophysiology of GDM by linking inflammation, adipose tissue dysfunction, and insulin resistance." (PMID 40943638, 2025). "The current study revealed that several cytokines—including RETN, CTSG, and ELANE, which can promote vascular damage and insulin resistance—were upregulated in the DM R+ group." (PMID 40641746, 2025). "In addition, the higher level of concentrations of adipocytokines are associated with fluctuations in the levels of angiotensinogen, plasminogen activator inhibitor-1, interleukin-6, and resistin, which might progress the onset of insulin resistance and atherosclerotic lesions." (PMID 38536210, 2024). "They showed that central resistin through TLR4 and activating the proinflammatory pathways induces insulin resistance." (PMID 38164476, 2024). "MD was associated with better prognosis after ischemic stroke, potentially mediated by lower insulin resistance, increased EPC mobilization, and lower resistin levels, among other factors." (PMID 39339817, 2024). "The representative adipokines secreted from adipose tissues with an increased plasma leptin, resistin, and TNF-α, and a reduced plasma adiponectin are related to systemic insulin resistance." (PMID 39065815, 2024). "Highly metabolically active visceral fat generates several pro-inflammatory adipokines, such as resistin, TNF-α, and IL-6, contributing to systemic inflammation, insulin resistance, and the onset of metabolic disorders." (PMID 39335642, 2024). "Nagaev and his co-authors contend that there exists a dearth of correlation between insulin resistance, T2DM, and resistin expression in both adipocytes and skeletal muscle." (PMID 39538244, 2024). "The accumulation of TG in adipocytes can lead to a rise in resistin, TNF-α, and interleukin 6, which can result in insulin resistance." (PMID 38867151, 2024). "Circulating biomarkers including insulin resistance (HOMA index), adipokines (resistin, adiponectin, leptin), choline pathway metabolites (TMAO, betaine, choline), and endothelial progenitor cells (EPCs) were measured." (PMID 39339817, 2024). "In particular, resistin, leptin, and PAI-1 induce insulin resistance by interfering with the expression of insulin receptor substrate-1 (IRS-1), negatively impacting insulin signaling in PLTs." (PMID 39858414, 2024). "OAGB was superior in T2DM control, which was in parallel with weight loss, fasting resistin levels, and HOMA-IR changes suggesting a possible effect of resistin after OAGB in glucose metabolism and insulin resistance." (PMID 38833355, 2024). "In summary, resistin appears to play a role in the development and progression of CRC, possibly through its involvement in inflammation, tumor growth, and insulin resistance." (PMID 39184804, 2024).
Insulin resistance (continued). "During pregnancy, insulin resistance increases, partly due to elevated levels of circulating adipocytokines: TNF-α, resistin, and leptin." (PMID 38069155, 2023). "Additionally, resistin is associated with the stimulation of lipolysis, which, combined with increased interstitial FFA may contribute to skeletal muscle inflammation and insulin resistance." (PMID 35980018, 2022). "Some adipocytokines such as adiponectin, leptin and resistin play important roles in the development of NAFLD by acting on liver by producing increased inflammation reaction and increasing insulin resistance." (PMID 36072931, 2022). "This reveals crosstalk at the hypothalamic level involving resistin, insulin, adiponectin, and FGF21 signaling pathways, which would be involved in HFD-induced neuroinflammation and insulin resistance." (PMID 36078135, 2022). "An uncomplicated pregnancy is characterized by insulin resistance, which increases with advancing gestation in order to secure a high glucose supply to the fetus; this may be attributed to hormones and cytokines, including TNFa, IL-6 and adipokines (resistin and leptin) produced by the placenta." (PMID 35885550, 2022). "A prior animal study has also demonstrated that mice can produce human resistin to improve WAT inflammation and insulin resistance under specific conditions stimulated by a high-fat diet." (PMID 36686437, 2022). "We have also shown that resistin at the hypothalamic level inhibits insulin signaling as well as that of adiponectin and FGF21, inducing hypothalamic and peripheral insulin resistance." (PMID 36078135, 2022). "Resistin, discovered in mice in 2001 and known as adipose tissue-specific secretory factor (ADSF) or found in inflammatory zone 3 (FIZZ3), is a 12.5 kDa cysteine-rich secreted protein that is involved in inducing insulin resistance." (PMID 35592858, 2022). "Therefore, resistin could lead to insulin resistance and inflammatory reaction." (PMID 34858392, 2021). "Measures of insulin resistance; fasting plasma insulin and homeostasis model of assessment for insulin resistance (HOMA-IR) were positively correlated with serum visfatin, resistin and fetuin-A." (PMID 34645898, 2021). "Quercetin can decrease resistin plasma concentration and gene expression, reduce LH and testosterone level in overweight or obese women with PCOS, and improve insulin resistance." (PMID 34306142, 2021). "Therefore, resistin could contribute to insulin resistance and inflammatory reaction." (PMID 34858392, 2021). "As a large amount of FFA, resistin, TNF-α, interleukin 6 and other compounds released by oversized adipose tissue can produce insulin resistance." (PMID 31801571, 2019). "For example, factors that are known to be related to insulin resistance, such as hyperinsulinemia and TNF-α, counter-regulate expression of resistin mRNA and protein in cultured adipocytes." (PMID 30886868, 2019). "Our recent findings evidenced that central Resistin/TLR4 signaling pathway promotes the onset of hypothalamic inflammation and insulin resistance." (PMID 30906281, 2019). "While age does not appear to affect resistin levels independent of fat mass, elevated levels of this adipokine are associated with an increased risk of cardiovascular disease in elderly men and women and insulin resistance in patients with a history of coronary intervention." (PMID 30915034, 2019). "The improvement in glucose tolerance and insulin sensitivity in TG9 mice correlated with a ~60% decrease in insulin resistance markers retinol-binding protein 4 (RBP4) and resistin in epidydimal fat pads isolated from ritonavir-treated animals." (PMID 29691457, 2018). "The relative ratios of studied adipokines (e.g. resistin/RBP4, leptin/MCP-1 and MCP-1/RBP4) are correlated with fasting glucose and HbA1c levels as well as with insulin resistance/sensitivity and β-cell function indexes." (PMID 29785210, 2018).
Insulin resistance (continued). "Although we did not observe a concomitant reduction in PPAR and CD36 in adipose tissue, we did observe reduction of the insulin resistance markers RBP4 and resistin in this organ." (PMID 29691457, 2018). "The present study aims to investigate the levels of leptin, resistin, visfatin, SFRP5, MCP-1/CCL2, and RBP4 as well as their correlations with insulin resistance and clinical parameters of overweight and T2DM in a Vietnamese study group." (PMID 29785210, 2018). "The tendency of lower resistin level is another positive HIG result, because the increase in this adipokine is related to the insulin resistance and worse inflammatory condition." (PMID 29412381, 2017). "In mice, HHcy promotes insulin resistance by directly inducing the expression and secretion of TNF-α and resistin." (PMID 27608037, 2016). "In addition, we also showed a significant positive correlation between some clinical and laboratory variables, including dyslipidemia and the levels of IL-6 and resistin which are adipocytokines that may contribute to insulin resistance and to the development of inflammatory responses." (PMID 25883983, 2015). "There is little direct evidence to link an increase in serum resistin with acquisition of T2DM, insulin resistance and metabolic syndrome." (PMID 26097512, 2015). "In addition, we also showed a significant positive correlation between some clinical and laboratory variables, including hypertension and the levels of IL-6 and resistin which are adipocytokines that may contribute to insulin resistance and to the development of inflammatory responses." (PMID 25883983, 2015). "The effects of resistin on the expression and localization of GLUT (glucose transporter) and on the development of insulin resistance have been extensively studied." (PMID 24692844, 2014). "Chronic inflammation of visceral adipose tissue (VAT) is a major contributor to insulin resistance mediated by adipose tissue-released adipokines (for example, IL-6, TNFα, MCP-1 and resistin)." (PMID 23837842, 2013). "This review article focuses on novel adipokines including visfatin, resistin, apelin, vaspin, and retinol binding protein-4 (RBP-4) and addresses their changes after bariatric surgery and their relationship to insulin resistance." (PMID 23772224, 2013). "Proteins including fetuin-A and resistin are reported to be endogenous ligands for TLR4 and induce insulin resistance." (PMID 24064574, 2013). "Recent data has focused on the roles of adipose tissue-derived mediators, such as adiponectin, leptin, resistin, tumor necrosis factor-alpha (TNF-α), visfatin, apelin, and chemerin in the pathogenesis of insulin resistance and inflammation." (PMID 23691290, 2013). "In visceral obesity, adipocytokines such as TNFα, resistin, IL-6 and FFA are secreted by enlarged fat cells of the internal organs as adipose tissue and induce insulin resistance." (PMID 22348333, 2012). "However, the detailed functions of resistin are still not understood; it has been appreciated that resistin can cause hepatic insulin resistance and that it may, along with its closely related homologs, interact with immune cells as well." (PMID 22645452, 2012). "The in vitro assays were analyzed in correlation with the biochemical and inflammatory profile of the subjects and with insulin resistance parameters (HOMA-IR, plasma resistin) as well." (PMID 22606013, 2012). "The AR index was more strongly correlated with the insulin resistance indexes and key metabolic endpoints of T2DM and MS than adiponectin and resistin levels alone." (PMID 21251282, 2011). "Among the existing insulin resistance indexes, quantitative insulin sensitivity check index (QUICKI) had the stongest correlation (P = 3.71 × 10-25) with the adiponectin-resistin (AR) index." (PMID 21251282, 2011). "The reduction in resistin levels achieved by GPS could potentially ameliorate the metabolic and vascular conditions in individuals with insulin resistance." (PMID 41378205, 2025).
Insulin resistance (continued). "The observed association between non-HDL-c and resistin in our study reinforces the role of non-HDL-c in promoting adipose tissue dysfunction, insulin resistance, and systemic inflammation." (PMID 40662131, 2025). "Studies showed that resistin is not necessarily related to the markers of adiposity—BMI, waist-to-hip ratio, fat mass or insulin resistance." (PMID 41011232, 2025). "Elevated resistin levels activate the c-Jun N-terminal kinase (JNK) pathway, which phosphorylates IRS-1 at serine residues, impairing its function and resulting in reduced glucose uptake and heightened insulin resistance." (PMID 41378205, 2025). "Drug-induced insulin resistance was attenuated, and the glucose uptake was four times higher in the presence of 10 ng/mL TNF-α and three times higher in the presence of 1 μg/mL resistin at a deuterium concentration of approximately 50 ppm relative to natural water." (PMID 39200235, 2024). "In individuals with NAFLD, lipotoxicity, insulin resistance, and endotoxins trigger the activation of proinflammatory cytokines such as tumor necrosis factor-α (TNF-α), interleukin-1α (IL-1α), interleukin-1β (IL-1β), interleukin-6 (IL-6), and resistin." (PMID 39275255, 2024). "Because adipose tissue with an excessive amount of FFA, resistin, TNF-α, interleukin-6, and other substances might result in insulin resistance." (PMID 37763170, 2023). "The mechanisms determining the action of resistin, a pro-inflammatory factor responsible for an insulin resistance (IR) development in humans, are not fully acknowledged." (PMID 36674022, 2023). "The notable effects of resistin on insulin resistance observed in rodents have not been consistently replicated in human studies, leading to a diminished interest in this molecule among diabetes researchers." (PMID 37761031, 2023). "On the other side, high-intensity PA induced an improvement in inflammatory biomarkers and insulin resistance, with a reduction in IL-6, TNFa, CRP, and resistin and an increase in adiponectin, thus indicating that exercise exerts anti-inflammatory and insulin-sensitising effects." (PMID 35679338, 2022). "In a recent meta-analysis, it was found that resistin levels in obese subjects with T2D were positively correlated with insulin resistance in subjects with hyperresistinemia but not in patients with normal circulating resistin levels." (PMID 35628332, 2022). "Even though resistin has been explored in numerous systemic disorders (e.g., atherosclerosis, insulin resistance), its potential clear role in the course of IBD has not been elucidated so far." (PMID 36235636, 2022). "Some studies reported that resistin served as an important regulator of contributing to insulin resistance while consistent results were not reported in another study." (PMID 34996484, 2022). "While some studies reported positive correlations between resistin and insulin resistance in T2DM, others failed to establish such an association." (PMID 35629157, 2022). "Thus, it can reduce fasting blood glucose and insulin resistance and reduce inflammation by decreasing serum levels of IL-6, TNF-α, and resistin and increasing serum levels of adiponectin and irisin, which ultimately improve insulin sensitivity." (PMID 36355818, 2022). "Finally, resistin levels were higher in the SIRD group and more closely related to diabetic nephropathy than insulin resistance." (PMID 34996484, 2022). "Additionally, HF and HF+FO/D groups showed insulin resistance, adipocyte hypertrophy, increased lipolysis and secretion of TNF-α, resistin and IL-10 adipokines by ING and RP adipocytes, and adiponectin only by the HF+FO/D group in ING adipocytes." (PMID 33652751, 2021). "Moreover, adipocytes secrete mediators of insulin resistance, namely, TNF-β, leptin, adiponectin, and resistin." (PMID 34595217, 2021). "Some studies show a significant relationship between resistin concentration and insulin resistance, while others do not confirm such a relationship." (PMID 34947881, 2021).
Insulin resistance (continued). "Four weeks of supplementation with TAN and HMF resulted in intermediate levels of blood serum glucose, leptin, resistin, and insulin resistance compared with the healthy control and the nonsupplemented HFD groups." (PMID 33841818, 2021). "The relationship between plasma resistin and insulin resistance is not clearly established in humans." (PMID 35011183, 2021). "Adiponectin levels has negative correlation, while leptin and resistin levels has positive correlation with insulin resistance in diabetic individuals." (PMID 33641315, 2021). "Arterial hypertension, dyslipidemia, older age, sedentary lifestyle, and abdominal obesity are key risk factors for T2DM since the adipose tissue secretes several biomarkers, such as resistin, TNF-α, and IL-6, which can induce a chronic inflammatory state and insulin resistance." (PMID 34012421, 2021). "There are studies showing a significant correlation between resistin concentration and insulin resistance; however, there are also data that do not confirm such a relationship." (PMID 32375231, 2020). "In female ddY mice subjected to bilateral ovariectomy (a model of insulin resistance), 12-week dietary pomegranate fruit extract (30 mg/kg/day) significantly reduced serum resistin levels without changing serum glucose." (PMID 33287432, 2020). "Because the role of resistin in the pathogenesis of insulin resistance and type 2 diabetes in humans has not been fully elucidated, further research in this area appears to be necessary." (PMID 32375231, 2020). "In this study, we found that serum PAI-1, adiponectin, resistin, and RBP4 levels were significant biomarkers for predicting the future progression to prediabetes or type 2 diabetes after adjusting for parameters related to inflammation and insulin resistance." (PMID 31690939, 2020). "Recently, resistin has been proposed as a marker of cardiovascular diseases and suggested to have a possible link to SAS; however, the relation between insulin resistance and resistin in humans remains unclear." (PMID 31013606, 2019). "Nevertheless, the relationship between resistin levels and insulin resistance has not been clarified in humans." (PMID 31803062, 2019). "Several studies found positive correlations between resistin and insulin resistance in T2DM, obese and healthy individuals; this discovery appears to be supported by studies reporting significantly higher resistin levels in populations with T2DM." (PMID 31803062, 2019). "In T2DM and obese individuals, resistin levels are positively correlated with insulin resistance in people with hyperresistinemia, but not in those with normal circulating resistin levels." (PMID 31803062, 2019). "Considering our results and these findings, RETN may be up-regulated in SAS patients and can lead them to insulin resistance/type 2 diabetes." (PMID 31013606, 2019). "Additionally, there was a positive correlation between plasma resistin levels and HOMA-IR, suggesting that increased resistin secretion promotes insulin resistance." (PMID 29601521, 2018). "At the same time, increased resistin levels found in smokers correlate with insulin resistance, while both in smokers and nonsmokers, they are not related to C-reactive protein, homocysteine, and uric acid levels." (PMID 30405857, 2018). "Exercise training decreased serum leptin, MCP-1, and resistin levels in db/db+Ex mice, but it did not reduce symptoms of insulin resistance including hyperglycemia, hyperinsulinemia, and impaired glucose tolerance." (PMID 29896118, 2018). "Adipocytokines such as leptin, adiponectin, resistin, interleukin-6 (IL-6) and tumor necrosis factor-α (TNF-α) are mediators produced by adipocytes which have important roles in the pathophysiology of insulin resistance, inflammation, hypertension, endothelial dysfunction and atherosclerosis." (PMID 28747175, 2017).